MMP9 (matrix metallopeptidase 9)
Diseases named in the same sentence as MMP9 in open-access papers (continued):
Sharing a sentence is not in itself a finding about the gene and the disease.
glioma (continued). "Among these, MMP-2 and MMP-9 are important effector molecules that enhance glioma cell invasiveness by breaking down extracellular matrix (ECM) components such as collagen and elastin." (PMID 36969167, 2023). "Mechanistically, we then assessed the protein levels of VEGFA, MMP2, and MMP9 in glioma cells after treatment with the miR‐143‐3p inhibitor and/or MEK‐2206." (PMID 36708044, 2023). "The in vitro experimental findings showed that SLC39A1 increased glioma cell proliferation, inhibiting apoptosis, and is possibly linked to the upregulation of MMP2/MMP9." (PMID 37298344, 2023). "Calycosin inhibits TGF‐N‐cadherin, Snail, Vimentin, MMP‐2 and MMP‐9 and inhibits glioma cell invasion and migration in vitro using the glial cell lines U87 and U251 in a dose‐dependent manner." (PMID 37675821, 2023). "SPOCK1 was reported to be a regulator of the ECM and is crucial for maintaining the process of tumor ECM dynamic homeostasis through regulating the activities and expressions of MMPs such as MMP-2, MMP-3, and MMP-9 in glioma, liver cancer, and prostate cancer." (PMID 36766694, 2023). "In a previous study, inhibition of cathepsin B and MMP-9 genes in glioma cells by RNA interference successfully reduced tumor growth and angiogenesis and inhibited tumor cell invasion." (PMID 37398678, 2023). "We observed similar results after KPF treatments on glioma cells in the MMP-9 inhibition expression level, even when the cells were stimulated using TPA." (PMID 37445894, 2023). "TGF-β1released from tumor-associated microglia promotes the expression of MMP-9 in GSC and maintains the characteristics of glioma stem cells, enhancing the aggressiveness of gliomas." (PMID 37700840, 2023). "It has been previously demonstrated that silencing of MMP-9, uPA, and uPAR leads to inhibition of glioma cell invasion." (PMID 37298344, 2023). "What makes this study interesting is that treatment of miR-211 and shRNA targeting MMP-9 together with temozolomide increased apoptotic DNA fragmentation in glioma CSCs as well as reduced drug efflux by Pgp, which is a well-known mechanism of chemoresistance." (PMID 35586209, 2022). "Clinicopathological analyses revealed that an elevated expression of SCIN in glioma patients was linked to an increased WHO grade and a poor survival, moreover, SCIN expression was positively correlated with MMP2 and MMP9 expressions." (PMID 36291348, 2022). "It was reported that PEDF downregulated MMP9 and inhibit invasion in malignant U251 glioma, MMP downregulation is same as our result, but the output is opposite." (PMID 35174090, 2022). "miR-4262 expression downregulation inhibits glioma proliferation and migration by suppressing the expression of MMP2 and MMP13, and miR-34a inhibits glioma cell migration by regulating MMP-9." (PMID 36479040, 2022). "Molecularly, phospho-STAT3, MMP2, and matrix metallopeptidase 9 (MMP9) are the targets of HNRPA2/B1 in glioma." (PMID 35625706, 2022). "The results indicated that the protein levels of IκB, P65, and MMP9 had decreased to varying degrees in two glioma cell lines." (PMID 34697897, 2022). "Overall, our study postulates a disturbance in the EGFR/MUC4/MMP9 signalling axis as a potential novel and rationalized biomarker panel for glioma." (PMID 36400876, 2022). "The miRNA was reported to be suppressed in high-grade glioma, and upregulation of miR-211 suppressed MMP-9 expression levels, which consequently reduced glioma cell invasion and migration." (PMID 35586209, 2022). "High expression of MMP2 and MMP9 has been described in glioma, correlated with tumor grade and localized to the cytoplasm of tumor cells, endothelial cells, and their extracellular matrix." (PMID 34980260, 2022). "Among them, 22 genes had a degree score ≥10 and 6 genes (WT1, HOXA2, HOXC6, MMP9, SHOX2 and MYOD1) were selected to construct a signature to classify glioma patients into low- or high-risk groups." (PMID 36118887, 2022).
glioma (continued). "We found that SCIN and MMP2/9 were upregulated in the primary glioma, SCIN had an excellent correlation with MMP2 and MMP9, and these proteins were closely related to the prognosis of a glioma." (PMID 36291348, 2022). "For example, in renal cell carcinoma cell lines, SAA promotes MMP9 expression, and in glioma cell lines it induces the secretion of not only MMP9 but also of IL-8 and ROS (Reactive Oxygen Species)." (PMID 36497411, 2022). "TGF-β signaling, subsequently activates a plethora of signal transduction pathways shown to trigger, among others, MMP2 and MMP9 expression by glioma cells thereby promoting invasiveness." (PMID 35992852, 2022). "MMP-1 and MMP-3 are associated with glioma invasiveness, MMP-2 and MMP-9 play a major role in invasion and migration, and MMP-9 is involved in angiogenesis." (PMID 36268515, 2022). "The majority of the antineoplastic activity of honeybee venom has been attributed to melittin through inhibition of VEGF, FLT-1, and MMP-9 in glioma C6 cells; metaloprotease-2 in human glioblastoma cells; and STAT3 and VEGF in glioma SHG44 cell." (PMID 39281062, 2022). "As already indicated, MUC4 and MMP9 can be detected and measured in tissue biopsies systematically collected in patients diagnosed with glioma." (PMID 36400876, 2022). "MMP9 expression and activity were previously reported to be preferentially displayed by high-grade gliomas and were suspected to be prognostic." (PMID 34980260, 2022). "In their study, they showed that POSTN promoted glioma cell invasiveness in vitro, accompanied by MMP-9 expression." (PMID 35163164, 2022). "The expressions of MMPs, including MMP-2 and MMP-9, have been shown to coordinate calcium mobilization and induce glioma cell metastasis." (PMID 35012441, 2022). "It is interesting to note that, upon direct TLR2 stimulation, CD44-/- microglia were still able to increase MMP9 production, while this ability was completely abolished in the presence of glioma cells." (PMID 35992852, 2022). "Then, we showed that MMP9 plasma level is correlated with glioma tissue RNA level and is released by tumor-infiltrating neutrophils from the glioblastoma microenvironment." (PMID 34980260, 2022). "In vitro studies indicate that BV has both cytotoxic and inhibitory effects on the secretion of MMP-2 and MMP-9 in selected lines of glioma, suggesting anticancer properties of BV." (PMID 35221898, 2022). "IHC staining of primary and recurrent glioma tissues suggested that the expression of HOXC6, MMP9, MYOD1 and SHOX2 are associated with the degree of hypoxia in gliomas as well in recurrent cases." (PMID 36118887, 2022). "As with other types of cancer, mechanisms implicated in gliomagenesis and glioma progression are regulated by multiple parallel pathways, thus other metalloproteinases, cell receptors or signaling molecules could very well act concurrently with MMP9 in promoting GBM invasiveness." (PMID 35992852, 2022). "MMP-2 and MMP-9 protein expression can be significantly upregulated upon miR-221/222 overexpression and promote proliferation and invasion of glioma cells in the presence of the Akt downstream pathway." (PMID 36479040, 2022). "We further performed Western blot analysis to examine the expressions of SCIN, MMP2, and MMP9 in 37 fresh frozen glioma samples and 6 normal tissues." (PMID 36291348, 2022). "CD44 knock-out in myeloid cells affected their ability to upregulate TNF-α and IL-1b, and most notably, to increase MMP9 production in response to gliomas." (PMID 35992852, 2022). "Immunoblotting analysis showed that after 48 h of treatment with PTE, the expression levels of MMP-2 and MMP-9 proteins in glioma cells were significantly reduced and dose-dependent." (PMID 33737656, 2021). "It is indicated that SP2 can regulate the expression of MMP2, MMP9, and VE-cadherin and promote the formation of VM in glioma cells at the transcriptional level." (PMID 33542193, 2021).
glioma (continued). "As reported in the literature, MMP2 and MMP9 are closely related to vasculogenic mimicry formation in gliomas." (PMID 33889541, 2021). "For example, Valentina reported that Serpine2 influences glioma cell migrative/invasive properties by regulating uPA and MMP-9/2 levels." (PMID 34689806, 2021). "Previous studies have shown that the high expression of MMP9 in tissues is an independent predictor of survival for patients with WHO grade III glioma tumors." (PMID 35154340, 2021). ", miR-885-5p overexpression was discovered to reduce the MMP-9 level, thereby suppressing the invasion abilities of glioma cells." (PMID 33430870, 2021). "The transcription factor SP2 directly bound to the promoter regions of the VM formation-related proteins MMP2, MMP9, and VE-cadherin, playing a role in promoting transcription in order to regulate the VM formation ability of glioma cells." (PMID 33542193, 2021). "Glycitein, a bacterial metabolite of the isoflavone glycitein, inhibits the expression of MMP‐3 and MMP‐9 in phorbol myristate acetate (PMA)‐stimulated U87MG glioma cells." (PMID 33300633, 2021). "Bioactive triterpenoid ursolic acid (UA) isolated from Rosmarinus officinalis was found to suppress IL-1β/ TNF-α and downregulate MMP-9 protein in rat glioma cells, thereby preventing cancer cell proliferation." (PMID 34439380, 2021). "U251 and U87 glioma cells transfected with pFv/nu dramatically suppressed the expression of p65, and NF‐κB‐dependent genes such as MMP‐9, VEGF, urokinase‐type plasminogen activator receptor and urokinase‐type plasminogen activator." (PMID 33300633, 2021). "In particular, miR-16 in glioma cells was upregulated negatively influencing the cell B cell CLL/lymphoma 2 (BCL2)/NFkB/Matrix Metallopeptidase 9 (MMP9) axis." (PMID 33672251, 2021). "Second, TTF application decreases the levels of VEGF, HIF1α, MMP‐2 and MMP‐9 via the suppression of NF‐κB, thus suppressing glioma angiogenesis." (PMID 33300633, 2021). "The overexpression of miR-211 also inhibits glioma cell invasion and migration via suppressing MMP9 expression." (PMID 33920915, 2021). "MT1 can also enhance the migration and invasion of human glioma cells by inducing matrix metallopeptidase 9 (MMP-9) activation through the upregulation of NF-kB p50 activity." (PMID 34804020, 2021). "MiR‐129‐5p overexpression obviously reduced the MMP‐2 and MMP‐9 protein levels and the luciferase activities of NF‐κB, indicating that miR‐129‐5p blocked the NF‐κB pathways to suppress glioma angiogenesis and growth." (PMID 33300633, 2021). "uPAR/MMP-9 silencing switches the glycolytic metabolism of glioma cells to oxidative phosphorylation (OXPHOS) and generates reactive oxygen species (ROS) to predispose glioma cells to mitochondrial outer membrane permeabilization." (PMID 33923400, 2021). "Microglia have been demonstrated to upregulate matrix-altering enzymes, especially MMP-2 and MMP-9, to facilitate glioma infiltration." (PMID 32172480, 2021). "Activation of MyD88-TLR-2 signaling by glioma released factors was found to increase the expression of MMP-9 of microglia." (PMID 34439380, 2021). "Mechanically, parthenolide attenuates NF‐κB transcriptional activity and the expression of NF‐κB targets, VEGF and MMP‐9, in glioma cells." (PMID 33300633, 2021). "Knockdown of SP2 significantly inhibited the mRNA and protein expression level of MMP2, MMP9, and VE-cadherin, thereby repressed the VM formation ability of glioma cells." (PMID 33542193, 2021). "In glioma, it is confirmed that ZNF-281 reduces glioma stem-like cells’ invasive ability via down-regulation of NF-κB1 and MMP9 protein expression in vitro and in vivo." (PMID 34071380, 2021). "MDSCs release vascular endothelial growth factor A (VEGFA) and matrix metalloproteinases (MMP2 and MMP-9) to promote glioma growth." (PMID 33452462, 2021). "MMP-9 and MMP-2 are associated with the integrity of the blood-brain barrier and have been shown to increase the invasiveness of human glioma cells." (PMID 32172480, 2021).
glioma (continued). "Innate migration and invasion of glioma cells is known to be promoted by MMP-9, which becomes activated by proteolytic cleavage of its exported precursor, pro-MMP-9." (PMID 33564720, 2020). "Increased levels of MMP-9 have been documented in the cerebrospinal fluid of dogs with intracranial tumors including histologically confirmed gliomas." (PMID 32258065, 2020). "Our results revealed that MMP-2 and MMP-9 expression in glioma cells were increased at both the RNA and protein levels after NE treatment, whereas CD147 silencing inhibited MMP-2 and MMP-9 expression (P<0.05)." (PMID 33178600, 2020). "Altogether, our results demonstrate that EN2 suppresses cell migration/invasion in glioma cells via MMP-9." (PMID 32158355, 2020). "Quercetin significantly reduces protein expression of phosphorylated ERK and Akt in A172 glioma cells, and decreases the expressions of MMp-9 and fibronectin which confers to decreased cell migration and cell viability." (PMID 33113890, 2020). "CCK-8 and flow cytometry results show that SLC39A1 promotes proliferation of glioma cells and inhibits their apoptosis; RT-qPCR and western blot results show that SLC39A1 promotes the progression of glioma by increasing the expression level of MMP2\MMP9." (PMID 33292262, 2020). "Another study showed that HIF induces TGF-β2, leading to the upregulation of MMP-2 and MMP-9 expression in human glioma cells." (PMID 32867190, 2020). "To reveal the molecular mechanism by which EN2 suppresses glioma cell migration/invasion, we examined and found that the protein level of MMP-9 was dramatically decreased by EN2 overexpression." (PMID 32158355, 2020). "O-Vanillin was able to attenuate the glioma-induced increase in mmp14 and mmp9 in cultured microglia as well as in microglia/macrophages isolated from human glioma samples." (PMID 32331440, 2020). "In vivo study using human glioma U-87 cells xenografted into athymic mice showed that curcumin is able to suppress glioma angiogenesis through inhibiting MMP-9 and downregulating endothelial cell markers." (PMID 33202681, 2020). "PIWIL1 also regulates apoptosis and cell cycle progression through P21, Cyclin D1, BCL-2 and BAX, and migration through expression of MMP-2 and MMP-9 in glioma cells." (PMID 31443431, 2019). "This study demonstrated that the ZRANB2/SNHG20/FOXK1 axis played an important role in regulating the expression of VM-related molecules MMP1, MMP9 and VE-Cadherin, and regulated the VM formation of glioma." (PMID 30744670, 2019). "FOXK1 down-regulates the levels of VM-related molecular MMP1, MMP9, VE-Cadherin by binding to their promoters and inhibited the VM formation in glioma cells." (PMID 30744670, 2019). "Co-transfection of SNHG20(−) cells with FOXK1(+) strongly decreased the expression of MMP1, MMP9, VE-Cadherin and strongly inhibited the abilities of proliferation, migration, invasion and VM of glioma cells." (PMID 30744670, 2019). "In the same paper, the authors showed a very weak MMP-9 mRNA expression in two of the four studied gliomas." (PMID 30062663, 2019). "FOXK1 significantly reduces VM-related molecules MMP1, MMP9 and VE-Cadherin and reduced VM in glioma cells." (PMID 30744670, 2019). "Microglial MMP9 is suggested to promote glioma motility and enhance angiogenesis via VEGF regulation." (PMID 31231208, 2019). "Previous studies have demonstrated that anti-apoptotic proteins, proliferative and metastasis-associated proteins (MMP-9 and VEGF), and cell invasion were reduced by specific inhibition of NF-κB activation in HCC, lung, and glioma cells." (PMID 30754643, 2019). "MMP-2 and MMP-9 have been described to play an important role in the migration, invasion, and metastasis of glioma cells." (PMID 31551765, 2019). "FOXK1 inhibited transcription by binding to the promoters of MMP1, MMP9 and VE-Cadherin and inhibited the proliferation and migration, invasion and VM formation of glioma cells." (PMID 30744670, 2019).
glioma (continued). "In an assay performed on glioma cell lines, it was found that epirubicin decreased the secretion of MMP-9 by about 50%, which suggests a potential antiproliferative and antimigratory role of epirubicin in this type of cells." (PMID 31514476, 2019). "A decisive role in glioma invasion is played by the gelatinases MMP-2 and MMP-9 and increased expression levels of MMP-2 is associated with glioma invasiveness." (PMID 30983966, 2019). "FOXK1 inhibits transcription by binding to the promoters of MMP1, MMP9 and VE-Cadherin and inhibits vasculogenic mimicry formation of glioma cells." (PMID 30744670, 2019). "Previous research has shown that matrix metalloprotease-2 (MMP-2) and MMP-9 expression are significantly elevated in high-grade gliomas." (PMID 30551687, 2018). "ANO1 is also involved in cell migration and invasion by regulating the expression of MMP2 and MMP9 in glioma cells." (PMID 29416639, 2018). "Several lines of evidence have also pointed out that plasma and/or serum levels of MMP-9 are elevated significantly with the degree of malignancy of gliomas." (PMID 28677624, 2017). "MiR-203 was found to inhibit glioma cell migration by disrupting the ROBO1/ERK/MMP-9 signaling axis." (PMID 28212562, 2017). "MMP-9 is a candidate biomarker for high-grade glioma that directs the migration and invasion of serum-stimulated GBM." (PMID 29029486, 2017). "Our results also showed that SAHA or/and MG132 decreased expression of MMP9 and Nanog in both glioma cells." (PMID 27911270, 2017). "In summary, our study revealed that PD-L1, VEGF, MMP-9 and KI-67 are all overexpressed in glioma, especially in HGG." (PMID 28591697, 2017). "The most evident findings was, indeed, the de-localization of the MMP-9 signal from glioma cells (nucleus and cytoplasm) to endothelial cells of neoplastic blood vessels, which is directly related to tumor malignancy." (PMID 27757720, 2017). "Knockdown of CLC-3 with ShCLC-3 adenovirus inhibits transcriptional activity of NF-κB, reduces MMP-3 and MMP-9 expression and decreases glioma cell migration and invasion." (PMID 28969029, 2017). "Other studies have also shown that glioma cells treated with cytochalasin D, another actin depolymerization agent, can influence MMP-9 expression and cancer cell invasion." (PMID 30931350, 2017). "MMP9 silencing decreased oncogenic c-Myc expression and induced senescence and apoptosis in glioma cells by inhibiting hTERT expression and telomere activity." (PMID 27022952, 2016). "Specifically, MMP-2 and MMP-9 are activated during angiogenesis and glioma invasion, and both of these enzymes can be measured in the CSF." (PMID 27876012, 2016). "The expression level of MMP9 was analyzed in different grades of glioma (Grade II, n = 126; Grade III, n = 51; and Grade IV, n = 128)." (PMID 27022952, 2016). "After confirming the elevation of MMP-9 levels in infected cells, the effect of MMP-9 inhibitor (SB-3CT) and dexamethasone was monitored in the infected C6 glioma cells." (PMID 27899068, 2016). "Meanwhile, the expression levels of MMP9 and MMP2 were higher in high-risk patients compared with the low-risk group, suggesting gliomas had increased invasion potential in the former group." (PMID 27677590, 2016). "Over expression of miR-203 drastically suppress Robo1 which in turn suppress ERK phosphorylation and MMP-9 expression thereby repressing glioma cell invasion and migration by disrupting the Robo1/ERK/MMP-9 signaling cascade." (PMID 27467502, 2016). "Matrix Metallopeptidase 9 (MMP-9) facilitates in the switch from repressive Mad/Max-bound state to activating c-Myc/Max-bound state of the hTERT promoter in glioma cells." (PMID 27548225, 2016). "MMP9 has been found in various cancer types, including glioma, lung cancer, pancreatic cancer and osteosarcoma." (PMID 27777384, 2016). "Effect of specific inhibition of MMP-9 on clearing the bacterial burden were further evaluated in C6 glioma cells infected with Mycobacterium tuberculosis H37Rv." (PMID 27899068, 2016).